MITF (melanocyte inducing transcription factor)
Diseases named in the same sentence as MITF in open-access papers (continued):
Sharing a sentence is not in itself a finding about the gene and the disease.
melanoma (continued). "Also, the relationship between MITF and NGFR remains unclear: While NGFR expression is elevated in melanoma with low MITF and has been identified as a direct target of MITF, we have not observed a consistent effect of NGFR overexpression on MITF expression in tumors in vivo." (PMID 36638181, 2023). "Moreover, such a mechanism may explain why melanomas enriched in immune cells that normally express low levels of MITF may not have an efficient anti-tumor immune response." (PMID 35912100, 2022). "Additionally, BMI1 epigenetic regulation demonstrates that melanoma cell states are not as binary (invasive or proliferative) as typically described; paradoxical epigenomic states exist which enable MITF alterations without proliferation changes or shifts in therapeutic BRAFi sensitivity." (PMID 36497341, 2022). "Moreover, some melanoma cells do not express MITF and display invasive properties." (PMID 35580987, 2022). "Furthermore, since a low MITF/AXL ratio was recognised as a predictor of early resistance, microRNA (miRNA) regulation of MITF expression was also explored as a novel therapeutic target to reverse the resistant phenotype among many other miRNA pathways dysregulated in melanoma." (PMID 36292642, 2022). "Additionally, small interfering RNA-mediated MITF silencing in melanoma cells significantly reduced melanin content by inhibiting tyrosinase, TRP-1, and MC1R, indicating that inhibition of the transcriptional activation of MITF is also a promising strategy to treat hypermelanogenic disorders." (PMID 34299326, 2021). "In conventional pan-melanoma-cocktail-negative cases, it is recommended to add, for an appropriate differential diagnosis, other markers such as the microphthalmia transcription factor (MITF) and the SRY-related high-mobility group box transcription factor 10 (SOX10)." (PMID 33801642, 2021). "While BRN2-mediated regulation of MITF is not likely to be important for non-melanoma cancers that do not express MITF, the ability of BRN2 to modulate PTEN expression uncovered here may play an equally important role in promoting the initiation and progression of these cancer types." (PMID 34140478, 2021). "However, there are no MITF-peaks in or near the TGFß1 gene in melanoma cells, leading us to hypothesize that the effects must be mediated through a hitherto unknown intermediary." (PMID 33438577, 2021). "While it was possible to obtain overlapping BRD4, BRD2, and MITF peaks on representative genes in different melanocytes and melanoma cells, we could not find BRD4, BRD2, and MITF ChIP-seq data for the same melanocyte or melanoma cell line to reliably quantify the overlap." (PMID 32151278, 2020). "Indeed, the expression levels of RBPJ and MITF exhibit a positive correlation (R=0.47, P<10−10) in the Genotype-Tissue Expression (GTEx) datasets for healthy skin (both sun-exposed and unexposed), but this correlation is absent in melanoma cells." (PMID 33628737, 2020). "However, dedifferentiated melanoma cells are not only characterized by a lack of MITF, but they frequently express receptor tyrosine kinases, which might affect drug resistance and immune control." (PMID 32978520, 2020). "Since melanomas can lose their differentiated phenotype, in part due to downregulation of MITF expression, and subsequently no longer contain identifiable melanosomes, this change could affect antigen processing and presentation and influence immune recognition." (PMID 33276788, 2020). "Despite MITF acts together with many transcription factors as SOX10, YY1, TFAP2A, LEF1, RB1, IRF4, and PAX3, its activity level determines the phenotype adopted by melanoma cells, whether invasive, proliferative, or differentiated according to the MITF rheostat model." (PMID 32850962, 2020).
melanoma (continued). "Notably, KD MITF was associated with a significant decrease in HERV-K expression (adjusted p-value < 0.01, Benjamini–Hochberg (BH) correction) in melanoma, but not in melanocytes, suggesting that MITF may regulate HERV-K expression specifically in melanomas." (PMID 33202765, 2020). "Additionally, we queried the TCGA melanoma pan-cancer dataset and segregated the patients as GHR-high (above mean GHR FPKM value; n = 117) and GHR-low (below mean GHR FPKM value; n = 354) to look at MITF and MITF targets as well as ABC-transporter expression levels in male and female patients." (PMID 31547367, 2019). "Furthermore, enforced expression of recombinant IL32α, -β, or -γ in M397 did not impact expression of melanoma differentiation genes MITF, AXL, NGFR or MLANA, strongly suggesting that IL32 is not a causal or upstream event in the melanoma dedifferentiation process." (PMID 30953519, 2019). "Finally, both SH3BP2 and MITF may also be useful targets, in other malignancies in which KIT is the driven molecule, such as acute myeloid leukemia (AML), mastocytosis, or certain cases of melanoma." (PMID 29885053, 2018). "However, proliferative and invasive phenotypes are not a characteristic of all melanoma cells within a single tumor, and a spectrum of MITF expressing and AXL expressing cells exist in any single tumor that can be manipulated through treatment with RAF and MEK inhibitors." (PMID 29383127, 2017). "Intra-vital imaging of an engineered mouse melanoma cell line, expressing GFP driven by a BRN2 promoter, has demonstrated motile, invasive cells leaving the site of the primary tumor had high expression of BRN2 while lacking pigmentation suggesting loss of MITF expression." (PMID 28883623, 2017). "Thus, the neural crest origin, but de‐differentiated nature of AXL‐high melanoma cells might explain why they express preferentially EDNRA, while differentiation towards the melanocyte lineage, triggered by MITF expression, results in a switch to EDNRB expression." (PMID 28606996, 2017). "Functions of PDLMI3 in melanoma development can only be speculated; in the adult, the protein is expressed in muscle and plays a role in disorders such as myotonic dystrophy type 1 (DM1) and SLC1A4 has been shown to be induced by the transcription factor MITF in the melanoma cell line SK-MEL-28." (PMID 27689402, 2016). "Moreover, while the expression of these melanoma differentiation antigens was back to basal level in patients on progression, in a patient who then was treated with a BRAF/MEK inhibitor combination, the MITF target genes were again upregulated in response to treatment." (PMID 26977879, 2016). "MITF is often referred to as the master regulator of melanocytes and melanoma cells and it is not surprising that it is differentially expressed in melanoma cell lines compared to cells from other cancer types (significance of differential expression of MITF: p = 2E-5)." (PMID 26927636, 2016). "Moreover, whether this is linked with MITF-driven alterations in the ELS affecting recycling and signaling properties of melanoma-associated RTKs has not been explored yet." (PMID 27896217, 2016). "Furthermore, AXL+/WNT5+ melanoma cells, lacking MITF expression, are highly invasive." (PMID 25818589, 2015). "Indeed, AXL+/WNT5A+ melanoma cells are resistant to MAPK pathway inhibitors and this might, at least in part, be due to the fact that the regulation of MITF expression is disconnected from BRAF." (PMID 25818589, 2015). "Consequently, tumors comprise a mix of MITF positive and negative melanoma cells." (PMID 25885555, 2015). "While MITF expression does not seem to be relevant in this melanoma cell population, both WNT5A and AXL expressions correlate with clinical response and therapy resistance, suggesting that assessing the AXL/WNT5A expression status could be used as prognostic and/or predictive marker." (PMID 25818589, 2015).
melanoma (continued). "In summary, as BRG1 knockdown downregulated expression of a large number of MITF-dependent and MITF-independent prosurvival proteins, our data suggest that a tissue-aimed inactivation of the SWI/SNF complex might become an effective approach in the therapy of melanoma." (PMID 23349796, 2013). "While other genes (e.g. CDKN2C, CDKN2A, MITF, BAP1, PTEN, ERBB4, and FGFR2, etc.)are mutated with some frequency in melanoma, no common recurring mutations in these genes are observed or the function of observed mutations are unknown; therefore these genes were not included in our screen." (PMID 22536370, 2012). "However, initial analysis points to a more complex mechanism since (i) the degree of changes in expression of these genes was often greater than that seen for MITF and (ii) expression of some pigmentation genes was found to be independent of MITF in some melanoma and melanocyte cultures." (PMID 21203491, 2010). "Importantly, we demonstrated that because ERK is constitutively activated in BRAF mutant melanoma cells, MITF is constantly degraded, a finding that is in agreement with the observation that MITF protein levels are generally lower in BRAF mutant melanoma cell lines than in primary melanocytes." (PMID 18628967, 2008). "BRN2 bound to a fragment (−77 to −20) of the MITF promoter in vitro, but not when the putative BRN2 binding site was mutated (data not shown) and chromatin immunoprecipitation (ChIP) assays showed that endogenous BRN2 binds to the proximal region of the MITF promoter in melanoma cells." (PMID 18628967, 2008). "Similarly, in the MIR155‐SOX10‐MITF FFL, miR‐155 may prolong the time required for producing the protein products of MITF or stabilize MITF expression against sudden activation or deactivation of SOX10 transcription to ensure desired melanoma cell phenotypic transitions." (PMID 40458894, 2025). "Unlike melanoma, GISTs predominantly express the longest MITF isoform, MITF-A, suggesting a distinct regulatory landscape." (PMID 41168571, 2025). "Among other established melanoma‐related genes that were included in our 360 gene panel and found negative in all index individuals were BAP1, TERT, and MITF." (PMID 40072281, 2025). "Our results revealed that the water extract of T. himalayense NIBR0000505337 not only effectively inhibited the expression of tyrosinase, TRP-1, TRP-2, and MITF, but also did not exhibit any signs of toxicity in B16F10 melanoma cells at 25, 50, and 100 μg/ml." (PMID 38480002, 2024). "Thin primary melanomas (such as MM28, Breslow = 0.8 mm) or thick primitive melanomas (such as MM25, Breslow = 16 mm) displayed a proliferative/differentiated ZEB2+ MITF+ SOX10+ phenotype with no or low ZEB1, SOX9 and NGFR expression." (PMID 38519642, 2024). "The first one is that miR-579-3p is specifically deregulated in the subset of BRAF-mutant melanomas but not in BRAF wt tumors and that its levels mirror those of MITF." (PMID 38472212, 2024). "These heterogenous melanoma subpopulations are characterized by the expression of MITFhigh and MITFlow proteins, MITF and BRN2 (non-canonical melanoma tumor-suppressor) proteins, and MITF and PAX3 proteins." (PMID 38275910, 2024). "Medium and low penetrance genes such as MITF and MC1R are more prevalent in the population, but alone, they are unlikely to result in melanoma development." (PMID 37762707, 2023). "The patient with BRAF (#56) V600+ mutant melanoma who carried both CDKN2A and MITF germline PVs did not respond to adjuvant therapy with TT nor to first-line treatment with ICI." (PMID 36901733, 2023). "For melanoma cases with a depth of less than 1.5 mm, none had high GREB1 expression (0/26), while only 11.5% (3/26) of these cases had high MITF expression." (PMID 37658191, 2023). "No mouse Greb1 gene expression was observed in the tissues and cell clone (Yummer1.7) from the mouse BRAFV600E; PTENflox melanomas nor in B16BL6 and B16F10 mouse melanoma cell lines expressing MITF target gene (Pmel)." (PMID 37658191, 2023).
melanoma (continued). "Both mOS-REp were positive for the melanoma markers S100, HMB-45, Melan-A and MITF, while OS-REp was unambiguously negative." (PMID 36175453, 2022). "We further observed that the primary tumors from SOX10– IGR-39 engrafted NSG mice remained negative for MITF and SOX10 protein expression, while we found scattered MITF+ melanoma cells in the primary tumors derived from SOX10+ MM383 engrafted NSG mice." (PMID 36040798, 2022). "Melanoma tumour progression and metastasis formation involves a pseudo-EMT process (given the non-epithelial nature of melanoma cells) in which MITF is also involved." (PMID 35682684, 2022). "However, some melanoma patients have metastatic disease without evident primary lesion and in this case, the disease development is associated with immunoediting mechanisms together with loss of immunohistochemical melanocytic markers like S100 protein, HMB-45, Melan-A, SOX10 and MITF." (PMID 35495634, 2022). "The non-immune cell clusters were made up of melanoma cells (MLANA, PMEL, MITF, DCT), endothelial cells (VWF, PECAM1) and fibroblast cells (COL1A1, COL3A1)." (PMID 36433984, 2022). "Although most types of malignant melanomas exhibit immunopositivity for these markers, desmoplastic melanomas are negative for MelanA/MART1, MITF, and HMB45." (PMID 35334544, 2022). "Disruption of MITF and its target CDKN2 has been shown to suppress growth and cell cycle progression in melanoma, but not in other cancers." (PMID 35008245, 2021). "Further analysis of the TCGA melanoma cohort showed that HERC5 and FBXO32 expression covaried with MITF; however, they were not correlated significantly with survival of patients with metastatic cutaneous melanoma." (PMID 33462405, 2021). "In particular, double IHC assays combining these markers with others for melanoma, although not tumor-exclusive (S-100, MART-1, Melan A and MITF), were performed to better identify foci of lymphatic invasion in melanoma." (PMID 34207514, 2021). "Namely, the unspecific was the most frequent dermoscopic pattern found in DN/melanomas of MITF+ patients (40%, as opposed to 9% in MITF− lesions)." (PMID 32054529, 2020). "Dermoscopically, the most common patterns of DN and melanomas (multicomponent, reticular-globular) were almost absent in MITF+ patients, while the multicomponent was the most frequent pattern among MITF− patients." (PMID 32054529, 2020). "In two different melanoma cell lines (SK-MEL-28 and HT144), we observed that transient knockdown of BRN2 reduced c-MET protein levels, whereas knockdown of MITF had no visible effect on c-MET level." (PMID 32632141, 2020). "We did not detect transcripts for melanoma antigens, gp100, Dopachrome tautomerase (DCT), Tyrosinase (Tyr), Melan-A and detected low levels of expression of Melanocyte Inducing Transcription Factor (MITF) in SB-3123p cells." (PMID 32231230, 2020). "We found that ANXA1, FZD7 and PTGR1 were MITF direct targets in CL1-0 cells, but these genes were not regulated in melanoma 501MEL cells." (PMID 33293474, 2020). "MITF, TFEB and TFE3 are expressed to some extent across melanoma tumors and cell lines, whereas TFEC is not." (PMID 32881934, 2020). "Nor is it clear whether melanomas exhibit a melanoma‐specific hypoxia signature compared to hypoxia in other cell types, whether some melanoma cells with distinct phenotypes exhibit a differential response to hypoxia, or whether MITF may contribute to the adaptive response to hypoxia." (PMID 31207090, 2019). "Competition-based regulation: In the absence of cells that express the Notch ligand in the melanoma microenvironment, RBPJK directly binds to MITF and enhances MITF-mediated transcriptional upregulation of its target genes." (PMID 30699982, 2019). "ECPS exhibitedantimelanogenic activity by down-regulating the expression of tyrosinase, MITF,and TRP-1 without cytotoxic effects in B16F10 melanoma cells." (PMID 29846408, 2018).
melanoma (continued). "SWI/SNF ATPases also promote the expression of prosurvivalgenes in melanoma cells that are not MITF dependent, indicating that BRG1 and the related BRM ATPasecoactivate multiple transcriptional regulatory factors in melanoma." (PMID 28521512, 2017). "The model provides that, although melanoma cells switch back to their embryogenetic program, PAX3 in CMM does not modulate MITF expression as it accounts for neural crest formation." (PMID 29156734, 2017). "While phenformin decreases melanoma CSC markers expression and the levels of the pro-survival factor MITF, MITF overexpression fails to prevent phenformin effects." (PMID 28036292, 2017). "Nelfinavir increased the amount of SMAD2 and consequently nuclear phospho-SMAD2 in melanoma cell lines in the absence of exogenous TGF-β, and, importantly, this correlated with the reduction in PAX3 and MITF expression." (PMID 26977879, 2016). "MITF-M expression was already reported to be suppressed in melanocytes and melanoma cells by several HDAC inhibitors (HDACi), and this MITF depletion did not reduce melanocyte viability." (PMID 26824319, 2016). "Nelfinavir also sensitized NRAS mutant melanoma cells to MEK inhibition and reduced PAX3 and MITF expression, whereas no sensitization was seen in the KRAS mutant colon cancer cell line HCT116." (PMID 26977879, 2016). "Nevertheless, BPTF likely acts as a cofactor for other transcription factors in MITF-negative melanoma cells and there are clearly genes regulated by BPTF, but not MITF, in MITF-expressing lines." (PMID 26440048, 2015). "Strikingly, despite the deregulation of RAF kinase signalling in melanoma and its relevance for melanoma development, so far it is not known what the global consequence of ERK‐mediated phosphorylation for MITF's transcriptional activity is." (PMID 25818589, 2015). "By contrast, in the WM115 melanoma cell line, even though PAX3 mRNA levels are low (compared to melanocytes), the complete lack of MITF can result in lack of translational interference though miR-211, allowing PAX3 protein translation." (PMID 25880082, 2015). "In tumors, five genes (KIT, MGMT, MITF, TERT, and TNF) exhibited methylation levels significantly different between tumor groups including acral compared to nonacral melanomas and matched primary lesions and metastases." (PMID 26106605, 2015). "Purified RSK1 is able to phosphorylate a 30aa S409 containing MITF peptide in vitro, and RSK1 can be co‐precipitated with MITF from melanoma cells after stimulation with KIT ligand, but not from untreated cells." (PMID 25818589, 2015). "Notably, BRN2-mediated repression of MITF transcription represents a mechanism distinguishing between melanoma cells and melanocytes due to the lack of BRN2 expression in the latter, which might be explained by the involvement of melanoma-specific BRAFV600E in BRN2 upregulation." (PMID 25433395, 2015). "We here describe that these features, expression of EGFR, lack of MITF and SOX10, are inherent and occurs independently of drug selection in EGFRHIGH/ERBB3LOW-Invasive melanomas." (PMID 25742786, 2015). "ATF2 control of melanoma development is mediated, in part, through its negative regulation of SOX10 and consequently, of MITF transcription." (PMID 24743024, 2014). "Cell morphology initially indicated malignant melanoma metastasis, but immunohistochemistry revealed diffuse positive results only for protein S-100, and negative results for malignant melanoma markers HMB45, Melan-A, MART-1 and MITF." (PMID 23108833, 2012). "Surprisingly, ATF2 control of melanoma development was mediated, in part, through its negative regulation of SOX10 and consequently of MITF transcription." (PMID 21203491, 2010). "Two of the four melanoma cell lines did not reveal increased SOX10 expression, although they retained increased MITF expression, upon inhibition of ATF2 (Lu1205, WM35)." (PMID 21203491, 2010).